MAL2 (mal, T cell differentiation protein 2)
Diseases named in the same sentence as MAL2 in open-access papers (continued):
Sharing a sentence is not in itself a finding about the gene and the disease.
malaria (1 paper, 2022). Malaria is a serious and sometimes fatal disease caused by a parasite that commonly infects a certain type of mosquito which feeds on humans. "Based on the stronger effect of Mal2 on fungus infection survival, and because of its physical proximity to the PRI locus for malaria susceptibility, the Mal2 locus on chromosome 2L was prioritized for further functional examination by candidate gene studies." (PMID 35428783, 2022).
malignant epithelial ovarian tumours (1 paper, 2010). "Immunohistochemical analyses of MAL2 and TPD52 expression were performed using tissue microarray sections including benign, borderline and malignant epithelial ovarian tumours." (PMID 20846453, 2010).
mucinous carcinoma (1 paper, 2010). "While high-level MAL2 and TPD52 staining were both frequent in mucinous carcinoma, and apparently increased stepwise from benign to borderline to carcinoma, this was not confirmed by comparisons of both visually and digitally-scored staining values." (PMID 20846453, 2010).
neuroblastoma (1 paper, 2023). Neuroblastoma (NB) is the most common solid, extracranial childhood tumor. "In aggressive clones of the SH-SY5Y human neuroblastoma cell line, copy number gain of MAL2 resulted in increased expression of MAL2 transcripts." (PMID 37345137, 2023).
oncocytoma (1 paper, 2023). "MAL2 mRNA and protein were found to be expressed in KICH but not in most oncocytoma, making MAL2 a promising biomarker to discriminate these two types of cancer." (PMID 37345137, 2023).
sarcoma (1 paper, 2021). A usually aggressive malignant neoplasm of the soft tissue or bone. "On the contrary, MAL2 expression decreased in some cancer types, such as sarcoma, brain and CNS, esophageal, kidney, and lymphoma cancer." (PMID 34567213, 2021).
cancer (33 papers, 2009 to 2025). A tumor composed of atypical neoplastic, often pleomorphic cells that invade other tissues. "Myelin and lymphocyte, T cell differentiation protein 2 (MAL2) is highly expressed in various cancers and associated with the development and prognosis of cancer." (PMID 34567213, 2021). "To further explore the MAL2 mutation in pan-cancer, we mined data from COSMIC and cBioPortal, which provide information about different kinds of mutation, including non-sense mutation, missense mutation, and synonymous mutations." (PMID 35111745, 2021). "In conclusion, we profiled MAL2 expression, survival rate, and mutation data across pan-cancers, which revealed the potential role of MAL2 in multiple types of cancer." (PMID 35111745, 2021). "The Catalog of Somatic Mutations in Cancer (COSMIC), cBioPortal, and UCSC databases were used to examine MAL2 mutation in human cancers." (PMID 35111745, 2021). "As the cancer progresses, Myc expression is further enhanced leading to Miz1 transcriptional repression and loss of Miz1-specific target expression—including MAL2." (PMID 32059473, 2020). "Because chromosome 8q24 amplification (where MAL2 resides) is associated with hepatocellular- and cholangio-carcinomas, we examined MAL2 protein expression in these human carcinoma lesions and adjacent benign tissue using immunohistochemistry." (PMID 32059473, 2020). "The overexpression of MAL2 was reported to be associated with increased gene copy in various cancers." (PMID 28562687, 2017). "Frequent reports of MAL2 overexpression in numerous cancer types, in association with increases in gene copy number, argue against MAL2 overexpression being an epiphenomenon." (PMID 20846453, 2010). "One such region occurs at chromosome 8q24.12, and includes the gene encoding the four-transmembrane protein MAL2, which is increased in copy number and/or overexpressed in breast and other cancers." (PMID 20846453, 2010). "Thus, the simple prediction is that enhanced MAL2 expression is associated with earlier stages of cancer progression and its expression is repressed during later stages and in metastases as Myc protein expression increases." (PMID 32059473, 2020). "Genomic instability gains in chromosome 8q24 (where MAL2 resides) are associated with several epithelial cell-derived human cancers and likely explains enhanced MAL2 transcript expression in at least a subset of these cancers." (PMID 32059473, 2020). "Further direct analyses are therefore required to determine whether MAL2 and MUC1 levels are positively correlated in cancer types commonly expressing these proteins, and whether MAL2 expression is significantly associated with cell surface expression of MUC1 in cancer cells." (PMID 19175940, 2009). "Application of the test on TCGA data revealed that MAL2 is significantly involved in the recycling step of the MHC-I pathway in seven cancer types." (PMID 39877095, 2025). "In this study, utilizing scRNA-seq, we discovered that the tetra-transmembrane protein mal, T cell differentiation protein 2 (MAL2), exhibited specific enrichment in ICC cancer cells and was strongly associated with a poor prognosis." (PMID 38866777, 2024). "LINC00460 expression is significantly elevated in BC tissues compared to normal tissues, promoting cancer cell proliferation and inhibiting ferroptosis by sponging miR-320a and upregulating myelin and lymphocyte protein 2 (MAL2)." (PMID 39763590, 2024). "The lack of association with clinicopathological features of TNBC indicates that MAL2 independently contributes to cancer progression." (PMID 38769215, 2024). "Despite their distinct mechanisms of action, MAL2 and PD-1/PD-L1 expression suppress immune surveillance and facilitate cancer progression." (PMID 38769215, 2024). "Recently, T Cell Differentiation Protein 2 (MAL2) emerged as a potential driver of cancer immune escape and novel therapeutic target." (PMID 38769215, 2024).
cancer (continued). "MAL2 knockdown inhibited cancer cell migration, invasion, and promoted apoptosis in vitro, and inhibited tumor metastasis in vivo possibly by regulating the EMT and β-catenin/c-Myc pathway." (PMID 37480012, 2023). "The analysis with cBioportal tools indicates that the percentage of MAL2 CNAs is positively correlated with the level of MAL2 transcripts in cancer, as was noted previously." (PMID 37345137, 2023). "Recent studies have reported that MAL2 acts as an influential regulator in cancers, mainly participating in endocytosis under physiological conditions and mediating the transport of intercellular substances." (PMID 37480012, 2023). "To study how prevalent is MAL2 in tumor samples, we analyzed transcriptomics data to compute MAL2 transcription levels in tumor specimens from the cancer genome atlas (TCGA)." (PMID 35437691, 2022). "The novel family member of MAL proteolipid, MAL2, is known to bind with tumor protein D52, thus participating in regulating the tumorigenicity of multiple human cancer types." (PMID 33634966, 2021). "MAL2 is located in chromosome 8q23, an area where the copy number often increases in various types of cancer." (PMID 34567213, 2021). "The results showed that MAL2 mRNA level was upregulated in multiple types of cancer, especially in OC, and MAL2 expression is significantly correlated with clinical stage among cancers." (PMID 35111745, 2021). "First, we confirmed the expression of MAL2 in human cancer tissues by comparing the transcriptome data between pan-cancer tissues and paracancerous tissues from TCGA using GEPIA database." (PMID 35111745, 2021). "In this study, we profiled a comprehensive investigation of the characteristics of MAL2 across 13 types of cancer based on multiple databases, including expression, survival analysis, and gene mutation." (PMID 35111745, 2021). "MAL2 gene mutation, methylation, function enrichment, protein–protein interaction (PPI), gene–gene interaction (GGI), cancer pathway activation, and drug sensitivity were comprehensively evaluated." (PMID 35111745, 2021). "Recent studies have reported that T-cell differentiation protein 2 (MAL2) is an important regulator in cancers." (PMID 35111745, 2021). "In our study, we first analyzed the MAL2 expression and clinical value in pan-cancers using Gene Expression Profiling Interactive Analysis (GEPIA) and Kaplan–Meier plotter databases." (PMID 35111745, 2021). "Gene Expression Profiling Interactive Analysis (GEPIA) databases was used to examine MAL2 expression in 13 types of cancer." (PMID 35111745, 2021). "How can MAL2’s function as a tumor suppressor be reconciled with its upregulated expression and link to bad prognosis in human cancers?" (PMID 32059473, 2020). "We propose a model to reconcile our findings of decreased MAL2 protein expression and its anti-oncogenic phenotypes with the findings from others that MAL2 transcripts are overexpressed in epithelial-derived cancers." (PMID 32059473, 2020). "This work was motivated by the finding that MAL2 is upregulated in a host of human epithelial-derived cancers at least at the transcript level." (PMID 32059473, 2020). "Surprisingly we found that MAL2 protein expression was significantly decreased in all three carcinomas, more consistent with MAL2 function as a tumor suppressor." (PMID 32059473, 2020). "To reconcile decreased MAL2 protein expression in human carcinomas and its anti-oncogenic phenotypes with increased transcript levels, we propose a transcriptional regulatory model for MAL2 transient overexpression." (PMID 32059473, 2020). "Recent studies report that the polarity gene myelin and lymphocyte protein 2 (MAL2), is overexpressed in multiple human carcinomas largely at the transcript level." (PMID 32059473, 2020). "Both Meta3 and Meta4 cells have high expression of many key markers of metaplasia, such as Wfdc2, Mal2, and Gpx2, and cancer stem cell (CSC) marker genes, such as Cd44, CD133 (Prom1), and CD166 (Alcam)." (PMID 31804471, 2019).
cancer (continued). "In the next step, we processed blood samples from 36 cancer patients and 12 healthy donors (cohort 1) using protocol A and measured the gene expression levels of EpCAM, MAL2, PPIC, and TUSC3 in the enriched cell fractions." (PMID 29416657, 2018). "In the present study, we found that MAL2 was significantly highly expressed in primary carcinoma tissues relative to adjacent mucosa tissues from CRC patients, implying that MAL2 was associated with tumorigenesis of CRC." (PMID 28562687, 2017). "Since MAL2 is known to be amplified and overexpressed in breast and other cancers, it is striking that MAL2 has now been shown to bind two proteins, MUC1 and D52, which are also amplified and/or overexpressed." (PMID 19175940, 2009). "Previous studies have suggested that the MAL2 gene may be involved in the transcytosis of various cancers." (PMID 38831979, 2024). "However, the unclear relationship between MAL2, PD-1, and cancer immune escape needs to be addressed." (PMID 38769215, 2024). "The amplification of MAL2 observed in most of the cancers examined is consistent with the presence of the MAL2 gene on chromosome 8q24, a region that is frequently amplified in cancer." (PMID 37345137, 2023). "It has been reported that MAL2 is significantly upregulated in diverse cancers." (PMID 37480012, 2023). "MAL2 has been identified as a mediator of various pathological conditions, including cancers." (PMID 37480012, 2023). "MAL2 gene upregulation has been observed in cancers affecting many organs, likely due to CNA." (PMID 37345137, 2023). "From the systematic analysis of MAL2 in pan-cancers, we found that MAL2 was significantly overexpressed and present with high mutation rate in OC samples, indicating that MAL2 may play a role in OC." (PMID 35111745, 2021). "Next, Kaplan–Meier plotter database was used to detect the prognostic value of MAL2 in pan-cancer." (PMID 35111745, 2021). "Some studies have shown that MAL2 functions as an oncogene in various malignant tumors." (PMID 33428596, 2021). "Kaplan–Meier plotter database was used to analyze the overall survival rate of MAL2 in pan-cancers." (PMID 35111745, 2021). "However, we determined that MAL2 protein expression levels are decreased in HCC, CC and RCC, displays an extremely low somatic mutation rate in human cancers and its function is more consistent with it being a tumor suppressor leaving us with a paradox." (PMID 32059473, 2020). "Surprisingly, we found that MAL2 protein levels were decreased in the malignant tissues compared to benign in all three carcinomas, suggesting MAL2 expression may be anti-oncogenic." (PMID 32059473, 2020). "The four-transmembrane protein MAL2 whose gene is located on chromosome 8q, commonly identified to be correlated with membrane apposition events, was found to be overexpressed or increased in copy number in some human cancers." (PMID 28562687, 2017). "MAL2 was shown to be overexpressed in a variety of human cancers." (PMID 28562687, 2017). "Additionally, like MAL2, TPD52 mRNA level was detected by RT-qPCR and showed an increase in carcinoma tissues, indicating its overexpression due to gene amplification.MAL2 is a heterologous binding partner of TPD52." (PMID 28562687, 2017). "Interestingly, both CCNE2 and MAL2 are located on chromosome 8q, a region which is frequently increased in copy number in breast and other cancer types, and one of the most important target genes affected by gains and amplifications of 8q is the MYC oncogene." (PMID 21129172, 2010). "The MAL2 gene was previously found amplified and overexpressed in breast and other cancers, yet the significance of this is unknown." (PMID 20932292, 2010). "Increased MUC1 localisation at the cell surface could reduce intercellular adhesion and promote invasiveness, and increased MAL2 expression would thus be expected to have adverse significance in cancer cells." (PMID 19175940, 2009).
cancer (continued). "The MAL2 gene, encoding a four-transmembrane protein of the MAL family, is amplified and overexpressed in breast and other cancers, yet the significance of this is unknown." (PMID 19175940, 2009). "However, overexpression of MAL2 in a colorectal cell line inhibited cell proliferation and invasion and suppressed tumorigenesis in xenograft in the same models, indicating that the role of MAL2 in cancer progression might be tissue-dependent." (PMID 37345137, 2023). "In order to further understand the clinical significance of MAL2, we selected the top three hub genes (MAL2, CDH1, and TPD52) from the GGI network to analyze their potential roles in drug susceptibility in OC according to the Cancer Therapeutics Response Portal (CTRP)." (PMID 35111745, 2021). "Therefore, one of the possible mechanisms of MAL2 in cancer may be related to the relevant signal pathway regulating cell adhesion." (PMID 35111745, 2021). "However, results from the NCI Genomic Data Commons (GDC) indicate that no such MAL2 mutations have been observed in almost 8000 patients representing 18 different cancer types." (PMID 32059473, 2020). "MAL proteolipid family (MALs), including T‐cell differentiation protein (MAL), T‐cell differentiation protein 2 (MAL2), and T‐cell differentiation protein like (MALL), were involved in the progression and prognosis of many different cancers." (PMID 40625454, 2024). "MAL (LUAD, THYM, and UCEC), MAL2 (BRCA, PAAD, and UCEC), and PLLP (KICH, KIRC, and UCEC) present strong correlations (p ≤ 0.001) in three types of cancer, and MALL (KIRC and PAAD), CMTM8 (KIRC and KIRP), and MYADM (LUSC and THYM) do so in two cancer types." (PMID 37345137, 2023). "Reports about promoter methylation of MAL-family genes in cancer are available only for MAL, MAL2, and MALL." (PMID 37345137, 2023). "MAL2 was originally identified by its interaction with TPD52-like proteins, a family of proteins frequently overexpressed in cancer." (PMID 37345137, 2023). "The detection of as few as 10 SKBR3 cancer cells isolated from a peripheral blood matrix (5 mL) was possible using the markers CK19, SCGB2A2, EpCAM, EMP2, MAL2 and PPIC." (PMID 36831613, 2023). "The association of mRNA expression of predicted target genes (PDCD6, GNG5, PHF6, MAL2, SLC25A15, PTDSS1) with clinicopathological parameters of BLCA patients were analyzed by UALCAN, containing BLCA individual cancer stages and molecular subtypes." (PMID 35503998, 2022). "Multivariate analysis indicated that transcriptional expression of predicted target genes (PDCD6, GNG5, PHF6, MAL2, SLC25A15 and PTDSS1) were significantly correlated with BLCA individual cancer stages and molecular subtypes." (PMID 35503998, 2022). "As proliferation and apoptosis are two key hallmarks of cancer, we performed CCK-8 and colony formation assays to evaluate the effect of MAL2 expression on cellular proliferation." (PMID 35111745, 2021). "The four-transmembrane protein MAL2 and tumor protein D52 (TPD52) have been shown to be involved in tumorigenesis of various cancers." (PMID 28562687, 2017). "MAL2 and TPD52 staining were also compared in carcinomas according to histological subtype, and here differences between MAL2 and TPD52 expression emerged." (PMID 20846453, 2010). "MUC1 represented a candidate partner of particular interest, given the fact that it is overexpressed in cancer types where MAL2 overexpression has also been reported, and as MUC1 overexpression contributes to cancer progression through a number of mechanisms." (PMID 19175940, 2009). "As MUC1 therefore represented a candidate MAL2 partner of particular interest, subsequent experiments were performed to confirm MAL2/MUC1 interactions, and examine their significance in breast epithelial and cancer cells." (PMID 19175940, 2009). "Results from the cancer genome atlas (TCGA) and clinical samples confirmed a significant upregulation of MAL2 in BC tissues than in adjacent non-tumor tissues." (PMID 37480012, 2023).